CT47A5 (cancer/testis antigen family 47 member A5)
Synonyms: CT47.5
Gene: Protein-coding gene on chromosome X (120,963,026 to 120,966,348, reverse strand). Ensembl gene ENSG00000237957.
Subcellular location (Human Protein Atlas): Nucleoli
Homologues: Orthologues: macaque CT47B1 (77% identical). Paralogues in human: CT47A1 (100% identical), CT47A10 (100% identical), CT47A11 (100% identical), CT47A12 (100% identical), CT47A2 (100% identical), CT47A3 (100% identical), CT47A4 (100% identical), CT47A6 (100% identical), CT47A7 (100% identical), CT47A8 (100% identical), CT47A9 (100% identical), CT47B1 (86% identical), and 1 more.